UQCRC2P1 (ubiquinol-cytochrome c reductase core protein 2 pseudogene 1)
Gene: Processed pseudogene on chromosome 3 (46,310,591 to 46,311,922, reverse strand). Ensembl gene ENSG00000236736.
Diseases named in the same sentence as UQCRC2P1 in open-access papers:
UQCRC2P1 is named in the same sentence as 2 diseases in open-access papers, as found by Europe PMC text mining. Sharing a sentence is not in itself a finding about the gene and the disease.
UQCRC2P1 shares sentences with these, for which no sentence is quoted: Autoimmunity (1 paper); COVID-19 (1).